GZMB (granzyme B)
Diseases named in the same sentence as GZMB in open-access papers (continued):
Sharing a sentence is not in itself a finding about the gene and the disease.
tumor (continued). "At baseline there was no apparent difference in CD8+ and CD8+Granzyme B+ (GrzB+) peripheral blood T cells between patients with pathological response (≤50% viable tumor cells) and nonresponders." (PMID 38689060, 2024). "Upon activation, naïve CD8+ T cells proliferate and differentiate to generate effector CD8+ T cells, which, in turn, synthesize copious amounts of cytotoxic effector molecules (Granzyme B and Perforin) and inflammatory cytokines (IFN-γ and TNF-α) that kill tumor cells." (PMID 38755598, 2024). "Subsequently, we evaluated the functional status of CD8+ T cells by analyzing intracellular IFN-γ and granzyme B (GZMB) production and evaluated CD8+ T cell exhaustion using the expression of PD-1 and Tim-3 on the cell surface in tumor-infiltrating lymphocytes (TILs) using flow cytometry." (PMID 38577598, 2024). "Immunohistochemistry (IHC) and flow cytometric analysis indicated that the numbers of tumor-infiltrating and splenic CD8+, Granzyme B+CD8+ and TNF-α + CD8+ T cells were higher in mice treated with APG-2575 + PD-1 blockade than in those treated with any single drug alone." (PMID 38062129, 2024). "While both Li and Mi exercise normalized the tumor vasculature, only Mi exercise increased tumor infiltrated CD8+ T cells, that also displayed enhanced effector function (higher proliferation and expression of CD69, INFγ, GzmB)." (PMID 38495879, 2024). "Furthermore, CAR-M was able to recruit and activate CD8+ T cells and increase GzmB and IFN-γ in the tumor tissue, whereas the regulatory T cell (Treg) population decreased significantly." (PMID 39061247, 2024). "Our experiments showed that knockdown of circRHBDD1 increased the percentage and number of CD8+ T cells in tumor tissues, along with elevated expressions of cytokines IFN-γ, TNF-α, and granzyme B, and reduced levels of coinhibitory molecules PD-1, TIM-3, and LAG-3." (PMID 39080693, 2024). "The expression of activation-specific genes (IFNG, GZMB, and TNFRSF9) and cell proliferation-specific genes (IL2, IL2RA, and CD28) decreased with the increasing rounds of tumor stimulation, especially from round 2 (the round in which tumor-killing ability begins to decline)." (PMID 39657666, 2024). "Consistently, we detected significantly increased infiltration and activation of CD8+ T cells in the shTrp63 group compared with the Scramble group in HNM007 tumor samples, as measured by the levels of activation and cytotoxic protein markers (CD69, GZMB, IFNγ) using flow cytometry analysis." (PMID 38509096, 2024). "Besides, cytotoxic factor expressions, such as GZMB and IFNG, were up‐regulated in combination treatment mice, indicating prominent tumor cell‐killing ability." (PMID 39422063, 2024). "Treatment with the PD-1 antibody alone could reactivate the tumor-infiltrated CD8+ T cells in H22 tumors by increasing the proportions of IFNγ+, TNFα+ and Granzyme B+ (GZMB+) cells within the CD8+ T cell population." (PMID 38684648, 2024). "For a comprehensive view of the tumor-infiltrating T cell landscape, the markers CD3, CD8, CD4, Programmed Cell Death Protein (PD)-1, granzyme B (GrzB) and Forkhead-Box-Protein P3 (FoxP3) were employed in addition to 4′,6-Diamidin-2-phenylindol (DAPI) nuclear staining." (PMID 38631706, 2024). "In addition, we also found that CD4+ and CD8+ T cells secreted PD-1, granzyme B, CD107a and TNF-α levels in tumor tissues of KC;Ubr7–/– mice were significantly reduced." (PMID 39424627, 2024). "In addition, we observed an increase in the expression of cytotoxicity (PRF1, GNLY, GZMB) and proliferation (MKI67) markers in the CD8+ T cells in PI3K/mTORi+PD‐1i‐treated tumours." (PMID 38711203, 2024). "Demonstrating the ability of VX-765 to induce an immunoreactive TIME within human tumors, treatment of humanized mice bearing MDA-MB231 xenografts decreased CD14+ HLA-DR+ macrophages and increased activated granzyme B positive (GrB+) CD8+ T cells, with a trend (p = 0.1) towards decreased tumor size." (PMID 39353903, 2024).
tumor (continued). "GzmB, CD20, and CD138 were expressed in the cytoplasm of tumour-infiltrating T and B lymphocytes." (PMID 38816839, 2024). "Interestingly, we observed that two CD8 GZMB+ subsets, one CD4 GZMB+ subset and one γδ T GZMB+ subset was predominantly derived from individual patients and were detected at both time points, suggesting that GZMB+ cytotoxic T cells may perform anti-tumor specific immune response in the TME." (PMID 39505839, 2024). "Interestingly, in the Sb9 KO tumors in Sb9 KO mice, there are increased ratios of CD8+, CD44+CD62L-CD8+, TNFα+CD8+, GzmB+CD8+, and IFNγ+CD8+, as compared with those from the WT tumor in WT mice." (PMID 38966643, 2024). "Preclinical studies across various tumor types demonstrate that HIFU, when combined with immunotherapy, increases the expression of IFN-γ and granzyme B in the distant tumor microenvironment, enhances CD8+ T cell activation, augments tumor cell lysis, and extends survival." (PMID 39612480, 2024). "However, it is worth noting that the presence of granzyme B in breast tumor tissue can degrade the TCR-zeta subunit in the TCR, thereby impeding TCR assembly, expression, and anti-tumor signaling." (PMID 38533507, 2024). "We assessed the most abundant cell type with clonal expansion in response to GOLP treatment, and found the exhaustion scores of CD8 GZMB+ were significantly decreased after GOLP treatment, suggesting that GOLP treatment reshaped immune-exhausted tumor environments." (PMID 38245530, 2024). "NK cells were still able to induce a slow death of virus-infected cells or tumor cells in the absence of GzmA and GzmB, most likely induced by orphan granzymes." (PMID 39061247, 2024). "CD8+ T cells play a key role in inhibiting the proliferation of tumor cells, and a high ratio of CD8+ T cells indicates remarkable bioactivity in eliminating tumors directly or indirectly through the release of granzyme B and perforin or the secretion of TNF-α and IFN-γ." (PMID 37308954, 2023). "Interestingly, although anti-PD-1 alone modestly affected the levels of tumor-infiltrating lymphocytes (TILs), the combination of anti-PD-1 treatment and VPRBP depletion induced a marked increase in TILs, including CD4+, CD8+/granzyme B+ T cells." (PMID 37024504, 2023). "Those two studies were the first to focus on the regulatory role of GzmB on tumor radioresistance rather than its direct apoptosis-inducing ability, which expand our knowledge on the biological functions of GzmB." (PMID 38264648, 2023). "In conclusion, these results highlight the intertumoral heterogeneity of granzyme B expression with low or absent expression in the majority of ccRCCs and a high expression in the tumor periphery in a subset of tumors." (PMID 37894418, 2023). "Furthermore, tumor cell-derived IL-6 and IL-8 activate molecular signals in NK cells that reduce the expression of activation markers (NKp30, NKG2D, and granzyme B), thereby impairing NK cell function." (PMID 37759302, 2023). "The intra tumoral/peritumoral ratio of CD8+ Granzyme B+ cells and density of intra-tumoral CD8+ CTLs is higher in patients with disease control than in those with progressive disease, revealing the importance of elevating tumor-killing T cells in UM." (PMID 37563735, 2023). "GzmB secreted by NK cells or other immune cells and GzmB synthesized by tumor cells are not identical." (PMID 38264648, 2023). "It has been illustrated that Granzyme B is not expressed in nTreg but is highly expressed in 5%-30% of tumor infiltrating Treg." (PMID 37936703, 2023). "Furthermore, the infiltration and activation of Vγ9Vδ2T (TCRδ2+ and Granzyme B+) and Car-B7H3-γδT cells (B7H3+ and Granzyme B+) peaked on day 7, with more activated Car-B7H3-γδT cells infiltrating the tumor tissue." (PMID 37770968, 2023).
tumor (continued). "To further confirm the combination effect of DDK inhibition and PD-1 blockade, we analyzed xenograft tissues by an IHC assay and found markedly increased abundance of tumor-infiltrated CD8+ T cells and granzyme B expression while decreased PD-1 expression in the combination therapy group." (PMID 37497004, 2023). "Treatment of MB49cPD-L1 tumors in the cPD-L1 mice with either the 12C or 3C antibody significantly reduced the tumor size, and increased the number of infiltrating cytotoxic T cells relative to mice treated with control IgG as measured by CD8 and granzyme B expression." (PMID 37377896, 2023). "MDSCs could inhibit T cell proliferation and function by down‐regulating the expression of IL‐2, INF‐γ, and granzyme B.38MDSC also reduces the number of CD8+ T cells and inhibits its cytotoxicity on tumor cells." (PMID 38023716, 2023). "Importantly, frequencies of tumor tissue-infiltrating PMN-MDSC were increased, while percentages of Granzyme B+ and Ki-67+ CD8 T cells were reduced in patients with HPV− disease." (PMID 38019346, 2023). "One of these DAMPs, called calreticulin, is exposed after EP, promoting the subsequent tumor infiltration by granzyme B-cells, However, its release was not enhanced only via exposure to a chemotherapeutic drug." (PMID 37999139, 2023). "In TME or TIME infiltrated B cells under the influence of IL-6, IL-1β, IL-12p35, and low oxygen (tumor-promoting molecules), which polarize to regulatory B cells (Bregs), producing TGF-β, granzyme B (GZMB), IL-10, and IL-35, which promote tumor growth and metastasis." (PMID 37275901, 2023). "IFN-γ and granzyme B are effective mechanisms through which CD8+ T cells kill tumor cells, which could directly contribute to the suppression of highly immunogenic tumor growth." (PMID 37901252, 2023). "As the first line of antitumor defense in the body, NKs can release perforin on the surface of target cells, resulting in cell perforation, allowing granzyme b to enter tumor cells to induce apoptosis and thus non-specifically kill tumor cells." (PMID 36843929, 2023). "They similarly suggested that there is not a single mediator of tumor killing but that perforin, granzyme A, granzyme B and granulysin in NK EVs together play prominent roles in inducing cytotoxicity." (PMID 37818374, 2023). "The triplet combination met its primary endpoint: demonstrating promising tumor microenvironment changes by significantly increasing the percentages of tumor-infiltrating activated T cells (CD3+ CD8+ CD137+ T cells) and activated, cytotoxic effector T cells (CD3+ CD8+ GZMB+ CD137+ T cells)." (PMID 37339979, 2023). "While some tumors showed a high number of granzyme B-positive cells in the tumor periphery, most ccRCCs did not follow this pattern." (PMID 37894418, 2023). "Results showed that combination therapy could inhibited tumor growth by transforming tumor with low immunoreactivity into inflamed (‘hot’) tumor, as demonstrated by increased CD8+granzyme B+ cytotoxic T cell infiltration." (PMID 36357599, 2023). "Furthermore, when combined with PD-1 mAb, the treatment resulted in more tumor-infiltrating CD8+ T cells and greater secretion of tumor-killing factors like IFN-γ, TNF-α, and GZMB." (PMID 37397393, 2023). "Tregs regulate anti-tumor immune responses through multiple mechanisms, including the production of adenosine through co-expression of CD39/CD73, granzyme B, perforin, or Fas/FasL pathways, and the development of tolerogenic DCs, leading to the formation of a regulatory T cell subset in the TME." (PMID 37834375, 2023). "Recent studies have shown that polyamine blocking therapy (PBT) reduced not only CD206+F4/80+ M2 macrophages but also tumor infiltrating cells including Gr-1+CD11b+ myeloid-derived suppressor cells (MDSCs) and CD4+CD25+ Tregs and concomitantly increased granzyme B+ and IFN-γ+ CD8+ T cells in TME." (PMID 37653021, 2023).
tumor (continued). "Similar to Sting-knockdown, we observed that treatment with C-176 significantly abrogated the anti-tumor effects of PD-L1 blockade therapy in Arih1-WT-OE tumors, together with decreased CD8+ and GzmB+CD8+ T cell infiltration, and reduced expression of ISG genes." (PMID 37429863, 2023). "This was associated with a reduction in granzyme-B positive intratumoural staining when compared with FAK-/- and FAK-/- STAT3 shRNA tumours, implying a lack of effective CD8 T-cell engagement in the context of FAK-wt tumours." (PMID 36977556, 2023). "Indeed, flow cytometry validated that tumor-infiltrating CD4+ T cells from the Ythdf1-KO group exhibited strong production of IFN-γ and granzyme B." (PMID 36650153, 2023). "Therefore, the association between Teffs and IPS was investigated by characterizing Teffs in the tumor nest versus the stroma using CD8A and GZMB." (PMID 36998102, 2023). "The primed and activated effector T cells gradually migrate and infiltrate into the tumor tissues, identify the tumor by specific T cell receptor (TCR) and antigen binding, and then release perforin, granzyme B (GZMB), and interferon-gamma (IFN-γ) to induce killing of tumor cells." (PMID 37397393, 2023). "In addition, we conducted a Spearman correlation analysis to investigate the relationship between the expression levels of LAMP3, GZMB, and CXCL13 proteins and the cellular composition of the tumor microenvironment." (PMID 37512096, 2023). "Flow cytometry analysis of LLC-tumor-bearing lungs at day 20 revealed an increased proportion of CD8+ T cells, CD4+ T cells and NK cells following IV BCG treatment, accompanied by enhanced cytotoxic potential evidenced by increased Granzyme B expression." (PMID 37794033, 2023). "Furthermore, we compared the infiltration and anti-tumor activity of anti-PSMA/anti-CD3 (scFv-Fab) BsAb-armed T cells and OKT3-T cells in the tumor area by CD8 and granzyme B immunohistochemical staining, respectively." (PMID 37259079, 2023). "Activated B cells also possess the tumor-killing potential and may directly destroy cancer cells by secreting TRAIL and granzyme B." (PMID 37046842, 2023). "However,tumor microenvironment (TME) with low GSDME expression has been found to have reduced tumor-infiltrating lymphocytes (TIL, CD8+ T and NK), GzmB, and perforin (PFN), potentially leading to an immunotherapy-unfavorable microenvironment in EC." (PMID 37965452, 2023). "As expected, this nanosystemnot only improved the tumor infiltration of Teff cells but also enhancedtheir cancer cell-killing activity against B16F10 melanoma by improvingsecretion of cytokines (e.g., IFN-γ and granzyme B)." (PMID 37901179, 2023). "As Granzyme B is an important cytotoxic molecule secreted alongside Perforin in granules by activated CD8+ T cells in order to induce apoptosis of target cells, these data imply that Kindlin-1 can impair the ability of T cells to mediate tumor cell killing." (PMID 36883731, 2023). "Similar to our PBMCs findings, following the co-incubation with K562 tumor cells, expression of NK cell functional markers (i.e., CD107a, IFN-γ, granzyme B, perforin) was significantly inhibited on the NK cells by stimulation with TP in a concentration-dependent manner." (PMID 36986557, 2023). "Furthermore, the expression of both granzyme A and granzyme B was highest in trNK cells and CD8+ TRM cells in the tumor center." (PMID 37448786, 2023). "Selected genes are reflecting main anti-tumor immune pathways, such as Th1 signaling (IFNG, TBX21, CD8A/B, IL12B, STAT1 and IRF1), Th1 chemoattraction (CXCL9, CXCL10 and CCL5) and cytotoxic functions (GNLY, PRF1, GZMA, GZMB and GZMH)." (PMID 37726776, 2023). "We observed that upon stimulation with tumor cells or tumor cells plus Obinutuzumab, the secretion of IFN-γ, Granzyme B, Perforin, Granulysin, and IL-10 was significantly increased in NK cells expressing hnCD16FR, whereas Granzyme A was secreted at high levels only in NK cells expressing hnCD16." (PMID 37316891, 2023).
tumor (continued). "Differential gene expression analysis indicated significant increases in inflammatory and effector gene expression, such as granzyme B (Gzmb) and CC-chemokine ligand 5 (Ccl5), in CD8+ T cells within the tumor microenvironment (TME) after PancVAX compared with isotype control–treated tumors (upper)." (PMID 38063199, 2023). "Interestingly, the tumors of PF patients showed a significant increase in stromal CD3+, GZMB+, FOXP3+, and CD11c+ cells compared with the tumor area." (PMID 37349318, 2023). "The deletion of PTPN2 in T cells not only promoted the activation and cytotoxic potential of tumor-infiltrating/resident T cells (as reflected by IFNγ, TNF and GZMB levels), but also enhanced STAT-1 signaling in AT3-OVA tumor cells, the expression of Cxcl9 and the recruitment of T cells." (PMID 37500611, 2023). "Moreover, circCRIM1 overexpression increased the infiltration proportion of Granzyme B, IFN-γ, and TNF-α positive CD8+ T cells and NK cells in the subcutaneous tumor via flow cytometry." (PMID 36672208, 2023). "However, significantly more tumor cell deaths and less secretions of cytokines (IL-6, IFN-γ, granzyme B and TNF-α) from the medium were observed in CRC cells with A20 overexpression than that in control cells and PBMCs co-culture system with matched HLA-A2." (PMID 37607946, 2023). "Granzyme B, derived from tumor‐infiltrating CD8+ T lymphocytes and NK, directly cleaves GSDME at the same site as caspase 3 to induce pyroptosis of target cells, thereby enhancing antitumor immunity and act as a tumor suppressor." (PMID 37125240, 2023). "Importantly, the overexpression of circCRIM1 suppressed the immune evasion of NSCLC and promoted the expressions of Granzyme B, IFN-γ, and TNF-α of CD8+ T and NK cell in vitro co-culture assays and tumor xenograft models." (PMID 36672208, 2023). "Additionally, they continued to express cytotoxic effectors (including GZMA, GZMB, GZMH) reflective of their anti-tumor potential." (PMID 38008725, 2023). "Depending on the cancer cell type and assay used, Vδ2 T cells are capable of tumor killing as well as cytokine, perforin, and granzyme B production in the absence of ZOL; in some cases, ZOL or other preconditioning is used to exert effective cancer killing." (PMID 37938576, 2023). "Immunohistochemically neoplastic cells are typically CD3+, CD7+, CD103+, TCRβ+/− cells, CD4−, CD8−, and CD5−, mostly expressing CD30 with CD56 negativity, and demonstrate an activated cytotoxic phenotype (perforin+, granzyme B+, and TIA-1+), reflecting the origin of the tumor from cytotoxic IELs." (PMID 37627888, 2023). "IL-21 is required for the generation of tumor-infiltrating CD8+ T cells expressing CX3CR1 characterized by cytolytic function and enhanced secretion of effector molecules such as interferon-γ and granzyme B." (PMID 36936961, 2023). "A previous study based on different syngeneic tumor models has shown that CD8+ T cells co-expressing inhibitory receptors (IRs) are not dysfunctional, but rather highly express activation and effector-related marker genes such as IFNG, GZMB, MKI67, and ICOS." (PMID 37773254, 2023). "As a consequence, the tumor immune microenvironment was remodeled, as evidenced by the reduced immunosuppressive MDSC, the amplifying NK cells and CD8+ T cells, and the increasingly released cytotoxic substances granzyme B and INF-γ." (PMID 37161591, 2023). "Furthermore, tumor-infiltrated CD8+ T and CD4+ T cells in the allografts highly expressed the activation/exhaustion markers, such as GZMB, GZMK, PDCD1, LAG3, HAVCR2, and CTLA-4." (PMID 37980406, 2023). "Notably, pretreatment of WT DCs with 2-DG reduced the numbers of tumor-infiltrating cGAMP-stimulated DCs, CD4+ T cells, and CD8+ T cells and decreased the frequencies of tumor-infiltrating IFN-γ–producing and granzyme B–producing CD4+ and CD8+ T cells." (PMID 36821379, 2023).